FOXD1 (forkhead box D1)
Diseases named in the same sentence as FOXD1 in open-access papers (continued):
Sharing a sentence is not in itself a finding about the gene and the disease.
tumor (55 papers, 2013 to 2026). "Emerging evidence suggests that FOXD1 expression is associated with aggressive tumor behavior in various cancers." (PMID 40083705, 2025). "FOXD1 knockdown experiments revealed that FOXD1 maintains the regulation of enhancers associated with tumor-promoting gene expression in basal-like cell lines." (PMID 37234983, 2023). "RNA sequencing (RNA-seq) and H3K27ac chromatin immunoprecipitation sequencing (ChIP-seq) experiments in basal-like cell lines with FOXD1 knockdown revealed that FOXD1 maintains distinct enhancer-gene programs associated with tumor progression." (PMID 37234983, 2023). "Univariate Cox regression analysis demonstrates that TNM stage, tumour differentiation and positive FOXD1 expression are prognostic risk factors for OS and DFS." (PMID 35579380, 2022). "We found that FOXD1 mRNA and protein expression were upregulated in PC tissues compared with non-tumor tissues, and high expression level of FOXD1 was associated with an adverse prognostic index of PC." (PMID 36057597, 2022). "The profound change in growth characteristics of tumor cells caused by loss of FOXD1 makes it an attractive therapeutic target, and since there is no reported strategy to inactivate FOXD1 itself, our work focused on the downstream pathways that are targetable." (PMID 36010951, 2022). "In previous work, we showed that FOXD1 expression correlates with poor patient outcomes in ccRCC, that its inactivation in ccRCC cells delays progression through the G2/M phase of the cell cycle, and that FOXD1 loss prevents tumor growth in a xenograft model." (PMID 36010951, 2022). "Phosphorylation of CDC2 and histone H3 is perturbed by the loss of FOXD1, suggesting that FOXD1 expression is an adaptation in tumor cells that promotes their proliferation by enabling their progression through the G2/M checkpoint." (PMID 36010951, 2022). "Recent studies showed that FOXD1 was associated with carcinogenesis, tumor progression, and metastasis in numerous cancers 14-16." (PMID 33403027, 2021). "In TCGA dataset, FOXD1 expression was significantly associated with tumor site (P=0.010) and HPV infection (P=0.010)." (PMID 34269372, 2021). "Inactivation of FOXD1 caused a significant reduction in cellular proliferation both in vitro and in tumor xenograft assays, and studies of cells with synchronized cycling times revealed that the G2/M phase of the cell cycle was extended in mutant cells." (PMID 33761914, 2021). "Tumor-associated macrophages (TAMs) infiltration increased in tissues with high FOXD1 expression in HNSC." (PMID 34028536, 2021). "The dysregulation of FOXD1 expression has previously been associated with malignant behavior in certain cancers and has been reported to contribute to aspects of tumor progression, such as drug resistance, metastasis, and stemness." (PMID 31795213, 2019). "Based on our findings, we postulate that FOXD1 is a critical TF that influences the epigenetic machinery underlying tumor progression and may be a potential therapeutic target." (PMID 37234983, 2023). "Despite this limitation, our study is clinically relevant because it reveals the correlation between poor prognosis and FOXD1 expression levels in basal-like primary tumors and indicates that FOXD1 maintains specific enhancer–gene programs associated with tumor progression." (PMID 37234983, 2023). "FOXD1 might be associated with tumor microenvironment and perhaps a potential target in the tumor immunotherapy." (PMID 35607308, 2022). "Moreover, multivariate COX regression analysis further demonstrated that TNM stage, tumour differentiation and positive FOXD1 expression are respectively independent risk factors in CRC patients." (PMID 35579380, 2022). "Although there is no functional proof that FOXD1 and BAP1 interact, due to the distinct FOXD1 expression pattern in UM it might be involved in diverting from a low-risk to high-risk tumor." (PMID 35954332, 2022).
tumor (continued). "We also found that high expression of FOXD1 was linked with tumour differentiation." (PMID 35579380, 2022). "Our data suggests that FOXD1 expression is necessary for proper cell division and may serve a protective role during mitosis in tumor cells predisposed to severe genetic damage." (PMID 33761914, 2021). "FOXD1 expression was significantly associated with tumor site and HPV infection." (PMID 34269372, 2021). "Previous studies have shown that FOXD1 may be an oncogene related to tumor development and act as a potential diagnostic biomarker and anti-cancer therapeutic target." (PMID 34772357, 2021). "High FOXD1 may be associated with tumor immunosuppression status." (PMID 34028536, 2021). "Mechanistically, FOXD1 promotes tumor cell stemness and chemoresistance by directly binding to β-catenin and enhancing its nuclear localization." (PMID 41614944, 2026). "In summary, our study elucidates a previously unrecognized regulatory mechanism in NPC pathogenesis, characterized by a mutually reinforcing FOXD1/NAT10 positive feedback loop that potently drives tumor progression." (PMID 40999468, 2025). "In NPC, FOXD1 enhances tumor development and gemcitabine resistance by facilitating mitophagy by activating BNIP3 transcription and expression." (PMID 40999468, 2025). "Targeting ALG3 in NPC with high FOXD1 expression prevented mitophagy and enhanced the anti-tumor activity of gemcitabine." (PMID 40083705, 2025). "FOXD1 promotes basal-like breast cancer progression by maintaining tumor-promoting transcriptional networks." (PMID 40999468, 2025). "IHC analysis corroborated these results, revealing a marked increase in FOXD1 protein levels within tumor tissues compared to non-tumor samples." (PMID 40083705, 2025). "NPC tissues displayed increased FOXD1 expression compared to paired non-tumor tissues, which correlated with worse overall survival (OS)." (PMID 40083705, 2025). "As compared to normal tissues adjacent to tumor, the mRNA levels of FOXD1 were significantly increased in tumor tissues." (PMID 41214670, 2025). "We further validated these findings using qPCR on NPC specimens, demonstrating that FOXD1 mRNA levels were indeed elevated in tumor (T) tissues compared with non-tumor (N) tissues." (PMID 40083705, 2025). "Remarkably, the combined knockdown of UBA2, RALY, and FOXD1 largely suppressed xenograft tumor growth and VM and prolonged nude mice survival." (PMID 37906341, 2023). "Further research has shown that miR-3oe-5p serves as a tumor suppressant by repressing the translation of FOXD1 through combining with the 3’-untranslated region (UTR)." (PMID 37563111, 2023). "Compared with the control groups, the sh-UBA2, sh-RALY, and sh-FOXD1 groups showed smaller tumor volumes." (PMID 37906341, 2023). "Remarkably, the combined knockdown of UBA2, RALY, and FOXD1 resulted in the smallest tumor volumes and the longest survivals of nude mice in vivo." (PMID 37906341, 2023). "Of the entire HNSCC tumor samples, 199 cases (59.6%) presented with a high expression level of FOXD1." (PMID 36983712, 2023). "Our mechanistic research suggested that miR-30e-5p is a tumor suppressor in HNSCC by post-transcriptionally repressing the translation of FOXD1 through binding to the 3’-UTR." (PMID 37563111, 2023). "Taken together, these findings suggest that FOXD1 modulates gene expression programs involved in tumor progression." (PMID 37234983, 2023). "We analyzed publicly available RNA sequencing data and conducted FOXD1-knockdown experiments, finding that FOXD1 maintains gene expression programs that contribute to tumor progression." (PMID 37234983, 2023). "CCK-8 assays also showed that the SCH772984 reduced the proliferation of FOXD1-overexpressing tumor cells." (PMID 36229838, 2022). "In these cases, the positive expression of FOXD1 was observed in 96 (73.3%) of the tumour specimens, while only 35 (26.7%) of the adjacent normal specimens presented a positive signal (p < 0.001)." (PMID 35579380, 2022).
tumor (continued). "It is noteworthy that, besides regulating BC migration and CTC formation, FOXD1 promoted tumor growth as well." (PMID 36229838, 2022). "In 90 paraffin-embedded pancreatic and non-tumor tissues, FOXD1 protein expression level was higher in PC(T) tissues than in non-tumor (N) tissues." (PMID 36057597, 2022). "Meanwhile TNM stage (p < 0.001), tumour differentiation (p = 0.004) and FOXD1 expression (p = 0.041) were independent prognostic factors for 5‐year DFS in post‐surgical CRC patients." (PMID 35579380, 2022). "Reproducing growth inhibition in tumor cells by inhibiting FOXD1 pathways presents a possible therapeutic approach for ccRCC and other cancers." (PMID 36010951, 2022). "Multivariate COX regression analyses confirmed that FOXD1 high‐expression, TNM stage and tumour differentiation were independent prognostic risk factor of OS and DFS." (PMID 35579380, 2022). "Clinical association studies and laboratory investigations have identified the FOXD1 transcription factor as a driver of tumor development." (PMID 36010951, 2022). "Subsequently, we analyzed the relation between FOXD1 expression and tumor microenvironment (TME), as well as the immune cell infiltration." (PMID 35607308, 2022). "We showed that the FOXD1 gene is directly controlled by tumor-suppressive miR-30e-5p in HNSCC cells." (PMID 35886008, 2022). "ESTIMATE and CIBERSORT algorithms were performed to assess the relationship of FOXD1 and tumor microenvironment and immune cell infiltration." (PMID 35607308, 2022). "To assess the tumor-promoting effect of FOXD1 in HNSCC cells, we performed knockdown assays using siRNAs." (PMID 35886008, 2022). "Accordingly, the results of H&E staining indicated that the xenografts carrying USP21 shRNA GSCs displayed restricted tumor growth, whereas this effect is reversed by overexpression of FOXD1." (PMID 35974001, 2022). "Results illustrated that FOXD1 high‐expression tumour samples showed a significant correlation with pathological differentiation (p = 0.021)." (PMID 35579380, 2022). "In 40 cryopreserved tissues, FOXD1 mRNA was found to be higher in 72.50% of PC(T) tissues compared with non-tumor (N) tissues." (PMID 36057597, 2022). "FOXD1 null tumor cells display aberrant cytokinesis and limited proliferation; replicating this phenotype in cancer cells presents an interesting therapeutic approach for ccRCC, and possibly other cancers." (PMID 36010951, 2022). "Following the commencement of SCH treatment, we observed an obvious reduction of tumor growth and tumor volume in the FOXD1-SCH group compared to FOXD1-vehicle." (PMID 36229838, 2022). "Together, these results suggest that disulfiram-induced FOXD1 ubiquitination contributes to the inhibition of tumor growth of patient-derived MES GSCs." (PMID 35974001, 2022). "Previous studies have also demonstrated that FOXA1 and FOXD1 are broadly involved in tumor development as well as mitochondrial metabolism." (PMID 36585925, 2022). "The multivariate analysis indicated that TNM stage (p = 0.001), tumour differentiation (p = 0.027) and positive FOXD1 expression (p = 0.044) were independent prognostic factors associated with OS." (PMID 35579380, 2022). "Some studies suggested that FOXD1 was involved in carcinogenesis and functioned as a tumor promoter in many cancer types." (PMID 34269372, 2021). "Structure-function studies of the FOXD1 protein and a better understanding of tumor architecture will be required to evaluate these possibilities." (PMID 33761914, 2021). "Given its role in promoting cell cycle progression and DNA damage repair, FOXD1 would be expected to confer a growth advantage, and for this reason it seems most likely that it is activated in subsets of cells as the tumor ages." (PMID 33761914, 2021).
tumor (continued). "In the present study, we found that FOXD1 was up-regulated in HNSC tissues at both mRNA and protein levels, and significantly associated with primary tumor site and HPV infection." (PMID 34269372, 2021). "In glioma, FOXD1 expression correlates with tumor grade and influences proliferation and migration of cells." (PMID 33761914, 2021). "FOXD1 expression was higher in patients with relatively high stages in several tumor types, including HNSC, BRCA, BLCA, ACC, KICH, READ, KIRP, and KIRC." (PMID 34028536, 2021). "In our study, we evaluated the expression of FOXD1 in various tumors in The Cancer Genome Atlas (TCGA) and its correlation with clinical features and prognosis of tumor patients." (PMID 34028536, 2021). "Nuclear FOXD1 was observed in all tumors, with extensive inter-tumor variability in proportion of positive nuclei." (PMID 33761914, 2021). "We show that FOXD1 regulates the cell cycle in ccRCC cells by control of histone H3 phosphorylation, and that FOXD1 expression governs tumor formation and tumor growth." (PMID 33761914, 2021). "Transcriptome analysis supports this role for FOXD1 in ccRCC patient tumors and provides an explanation for the inverse correlation between tumor expression of FOXD1 and patient survival." (PMID 33761914, 2021). "Taken together, our data shows that FOXD1 is required for 786-O tumor cells to undergo mitosis with DNA damage repair of both daughter cells." (PMID 33761914, 2021). "Patients with FOXD1-low tumors showed significantly higher probability of survival at all time-points analyzed, supporting a role for tumor expression of FOXD1 in disease progression." (PMID 33761914, 2021). "This study uncovers a novel and important role for FOXD1 in controlling division and DNA repair of ccRCC tumor cells." (PMID 33761914, 2021). "On the other side, there are also nuclear markers, such as FOXD1, that have been suggested as a potent driver of tumor growth in ccRCC." (PMID 35008363, 2021). "In support of this possibility, co-knockdown not only resulted in a reduction of FOXD1 and Gal-3 expression but also further suppressed tumor growth and motility." (PMID 31795213, 2019). "FOXD1 plays important roles in a great number of biological processes, for example, cell proliferation, carcinogenesis and tumor metastasis." (PMID 30627052, 2019). "Dysregulation of forkhead box D1 (FOXD1) is known to promote tumor progression; however, its molecular mechanism of action is unclear." (PMID 31795213, 2019). "It is well documented that FOXD1 contributes to aggressiveness by targeting different downstream molecules in various tumor types." (PMID 31795213, 2019). "FOXD1 (forkhead box protein 1) has a role in tumor formation, while AVEN (apoptosis, caspase activation inhibitor) has an established role in apoptosis regulation." (PMID 23445407, 2013). "Furthermore, FOXD1 depletion inhibited tumor growth, decreased Ki67 expression, increased Caspase 3 expression, and promoted cell apoptosis." (PMID 40083705, 2025). "FOXD1, a crucial transcription factor, acts as a tumor-promoting factor in NPC." (PMID 40999468, 2025). "Emerging studies delineate FOXD1 as a critical mediator of tumor vasculature." (PMID 40999468, 2025). "Secondly, since the characteristics of CAMTA2 and FOXD1 in NB remains unclear, more real-world researches enrolling more tumor specimens, as well as more experiments in vitro or in vivo should be carried out to explore their biological function in NB." (PMID 38512513, 2024). "Hence, we performed pan-cancer analysis to reveal the heterogeneity of CAMTA2 and FOXD1 expressions in tumor and normal samples across 33 tumor types." (PMID 38512513, 2024). "FOXD1 has been reported to promote tumor progression in many cancer types." (PMID 37563111, 2023). "Collectively, these data suggested that FOXD1 may promote tumor malignancy in HNSCC by inducing the p21/CDK2/Rb pathway." (PMID 37563111, 2023).
tumor (continued). "Physiological and pathological studies on the role of the FOXD1-BCL-2 axis may provide insights into tumour occurrence and progression." (PMID 38092733, 2023). "miR-30e-5p serves as a tumor suppressor inhibiting the FOXD1-mediated progression of HNSCC." (PMID 37563111, 2023). "Further, they highlight that FOXD1 may be an oncogenic TF that activates tumor-promoting gene expression programs by modulating enhancers." (PMID 37234983, 2023). "Thus, the present results in combination with previous literature suggest that FOXD1 is a factor that promotes tumor cell malignancy through various pathway." (PMID 37563111, 2023). "A more tractable strategy is to modulate pathways regulated by FOXD1, and in this study we used a transcriptomic analysis to identify specific pathways downstream from FOXD1 that can be pharmacologically modulated to suppress the G2/M transition in ccRCC tumor cells." (PMID 36010951, 2022). "In this study, we identify USP21 as a novel upstream regulator which interacts with and stabilizes FOXD1 and show that genetic or pharmacological inhibition of USP21 abrogates MES GSC-derived tumor growth in vitro and in vivo by antagonizing FOXD1 ubiquitination and degradation." (PMID 35974001, 2022). "Moreover, TNM stage, tumour differentiation and positive FOXD1 expression are capable of predicting 3 and 5 years of survival in the Nomogram model." (PMID 35579380, 2022). "Moreover, TNM stage, tumour differentiation and positive FOXD1 expression can be used to predict 3 and 5 years of survival in the Nomogram model." (PMID 35579380, 2022). "Our analysis of the TCGA and GTXs data also showed that FOXD1 expression was higher in PC tissues than in non-tumor tissues and that FOXD1 expression-related genes were significantly enriched in a number of pathways, namely PATHWAY_IN_CANCER, PANCREATIC_CANCER, and GLYCOLYSIS_ GLUCONEOGENESIS." (PMID 36057597, 2022). "Silencing FOXA1 or FOXD1 in RCC inhibits tumor growth by inhibiting cell cycle progression." (PMID 36585925, 2022). "As tumor was progressing, the effect of FOXD1 on tumor growth became pronounced, which might further quicken the formation of CTCs." (PMID 36229838, 2022). "Our analysis of FOXD1 targets revealed three therapeutically interesting candidates and demonstrated profound effects of their growth inhibition on both 786-O and primary patient tumor cells." (PMID 36010951, 2022). "Forkhead box D1 (FOXD1) plays an oncogene role in a variety of tumor types." (PMID 35740551, 2022). "Overexpression of FOXD1 was observed in the cytoplasm of tumour cells." (PMID 35579380, 2022). "We analyzed tumor samples from TCGA database to identify FOXD1 expression characteristics." (PMID 34269372, 2021). "Moreover, FOXD1 can promote tumor progression and therapeutic resistance by inhibiting P27 mRNA expression in breast cancer." (PMID 34772357, 2021). "Of note, the inhibition of FOXD1 expression affected cell related malignant phenotypes such as cell proliferation, cell migration and invasiveness, cell apoptosis and ultimately leads to tumor regression and reduction of tumor metastasis." (PMID 34772357, 2021). "This work supports a role for FOXD1 as a potent driver of tumor growth in ccRCC." (PMID 33761914, 2021). "It is clear that there were no obviously association between FOXD1 abundance and patients age, drinking and heavy tobacco usage, tumor size and pathological grading." (PMID 34772357, 2021). "To understand if there could be a role for FOXD1 in ccRCC, we correlated tumor expression with patient outcomes using data from The Cancer Genome Atlas (TCGA)." (PMID 33761914, 2021). "In addition, FOXD1 is further proved to regulate the cancer stem cells properties including tumor initiation, chemotherapy resistance and self-renewal capacities on mesenchymal glioma cells." (PMID 34772357, 2021). "FOXD1 is involved in the progression of many diseases, including several tumor types." (PMID 34028536, 2021).